JMJD7 (jumonji domain containing 7)
Description:
Bifunctional enzyme that acts both as an endopeptidase and 2-oxoglutarate-dependent monooxygenase. Endopeptidase that cleaves histones N-terminal tails at the carboxyl side of methylated arginine or lysine residues, to generate 'tailless nucleosomes', which may trigger transcription elongation. Preferentially recognizes and cleaves monomethylated and dimethylated arginine residues of histones H2, H3 and H4. After initial cleavage, continues to digest histones tails via its aminopeptidase activity. Additionally, may play a role in protein biosynthesis by modifying the translation machinery. Acts as a Fe(2+) and 2-oxoglutarate-dependent monooxygenase, catalyzing (S)-stereospecific hydroxylation at C-3 of 'Lys-22' of DRG1 and 'Lys-21' of DRG2 translation factors (TRAFAC), promoting their interaction with ribonucleic acids (RNA).
Tractability: Small molecule: a structure with a bound ligand is known. PROTAC: ubiquitination databases record sites on it; its protein half-life has been measured; a small molecule that binds it is known.
Target class: Enzyme; Oxidoreductase
Gene: Protein-coding gene on chromosome 15 (41,828,092 to 41,837,585, forward strand). Ensembl gene ENSG00000243789.
Subcellular location: Nucleus; Cytoplasm
Subcellular location (Human Protein Atlas): Cytosol
Pathways (Reactome):
Metabolism of proteins: Protein hydroxylation
Gene Ontology:
Molecular function: aminopeptidase activity; endopeptidase activity; monooxygenase activity; peptidyl-lysine 3-dioxygenase activity; protein binding
Biological process: protein hydroxylation; peptidyl-lysine hydroxylation
Cellular component: cytoplasm; nucleus; cytosol
Genetic constraint (gnomAD): Loss-of-function variants: 41 observed, 38.44 expected, observed/expected ratio (o/e) 1.07, 90% interval 0.83 to 1.38. The upper end of that interval is the gene's LOEUF score, 1.38, which puts it in group 5 of 6, group 1 being the genes least tolerant of losing a copy. Missense variants: 480 observed, 412.85 expected, observed/expected ratio (o/e) 1.16, 90% interval 1.08 to 1.25. Synonymous variants: 202 observed, 169.39 expected, observed/expected ratio (o/e) 1.19, 90% interval 1.06 to 1.34.
Homologues: Orthologues: chimpanzee JMJD7 (96% identical), dog JMJD7 (92% identical), pig JMJD7 (92% identical), rabbit JMJD7 (91% identical), mouse Jmjd7 (90% identical), rat Jmjd7 (90% identical), zebrafish jmjd7 (64% identical), Drosophila melanogaster JMJD7 (44% identical). Paralogues in human: TYW5 (21% identical), KDM8 (20% identical), HIF1AN (18% identical), HSPBAP1 (18% identical).
Diseases named in the same sentence as JMJD7 in open-access papers:
JMJD7 is named in the same sentence as 12 diseases in open-access papers, as found by Europe PMC text mining. Sharing a sentence is not in itself a finding about the gene and the disease. The quoted sentences say what the papers report.
breast carcinoma (2 papers, 2017 to 2023). "Not only is JMJD7 upregulated in head and neck squamous cells, its knockdown or a defective, enzymatically inactive variant of JMJD7 in breast cancer cells significantly reduces cell growth." (PMID 37218871, 2023). "JMJD7 and JMJD7-PLA2G4B genes were also expressed in various human colon and breast cancer cell lines." (PMID 28030848, 2017).
autism (1 paper, 2022). Persistent deficits in social interaction and communication and interaction as well as a markedly restricted repertoire of activity and interest as well as repetitive patterns of behavior. "These links to cancer and autism make JMJD7 a compelling enzyme to study from the perspective of linking oxygenase activity to physiology and disease, including by using appropriate models to study JMJD7 function at an organismal level." (PMID 35410347, 2022).
Headache (1 paper, 2018). Cephalgia, or pain sensed in various parts of the head, not confined to the area of distribution of any nerve. "We identified numerous genes associated with headache, both temporal and other types: POFUT2 in CD4 cells, and SLC35F6, HTD2, ZNF708, KLRC4-KLRK1 and JMJD7 in CD8 cells." (PMID 30037347, 2018).
lung adenocarcinoma (1 paper, 2022). A carcinoma that arises from the lung and is characterized by the presence of malignant glandular epithelial cells. "TRDMT1 and JMJD7.PLA2G4B genes were downregulated, while the other 10 genes were significantly overexpressed in lung adenocarcinomas compared with normal tissues." (PMID 35812404, 2022).
mesothelioma (1 paper, 2011). A usually malignant and aggressive neoplasm of the mesothelium which is often associated with exposure to asbestos. "We have analyzed a total of 4 genes: 2 genes that are up-regulated in H342-treated H2373 mesothelioma cells (Fos, JMJD7) and 2 genes that are down-regulated (SNIP1, SMAD6)." (PMID 21998702, 2011).
cancer (3 papers, 2020 to 2022). A tumor composed of atypical neoplastic, often pleomorphic cells that invade other tissues. "Knockout of JMJD7 in a human cancer cell line dramatically represses the growth of the cell, suggesting a critical role in cell proliferation." (PMID 35327545, 2022). "The JMJD7 gene, located on human chromosome 15, can form a naturally occurring read-through transcript with the neighbouring PLA2G4B gene to encode a JMJD7-PLA2G4B fusion protein overexpressed in cancers, including breast, prostate, and thyroid cancer." (PMID 35410347, 2022). "In this regard, inhibitors of JMJD5, JMJD6, and JMJD7 could be effective anticancer drug targets to treat different cancers." (PMID 35327545, 2022).
tumor (1 paper, 2024). "The incomplete JmjC domain predicts the absence of any enzymatic activity so that the functions of this fusion protein likely match those of phospholipase A2, making it difficult to distinguish the worth of JMJD7′s contribution in such tumor tissues." (PMID 39000010, 2024). "Curiously, a natural readthrough transcription between the JMJD7 locus and the downstream neighbor phospholipase A2, group IVB (PLA2G4B), occurs in tumor tissues, encoding the fusion protein JMJD7-PLA2G4B including a partial JmjC domain and the C2 and phospholipase A2 domains." (PMID 39000010, 2024).
JMJD7 also shares sentences with these, for which no sentence is quoted: bipolar disorder (1 paper); head and neck squamous cell carcinoma (1); intellectual disabilities (1); schizophrenia (1); squamous cell carcinoma (1).